OTULIN (OTU deubiquitinase with linear linkage specificity)
Diseases named in the same sentence as OTULIN in open-access papers (continued):
Sharing a sentence is not in itself a finding about the gene and the disease.
colitis (1 paper, 2023). Inflammation of the colon. "We show that mice with intestinal epithelial cell (IEC)-specific OTULIN deficiency exhibit increased susceptibility to experimental colitis and are highly sensitive to TNF toxicity, due to excessive apoptosis of OTULIN deficient IECs." (PMID 37598207, 2023). "Although OTULINIEC-KO mice and WT littermate control mice showed a similar disease progression with maximal clinical colitis on day 8–9, OTULIN deficiency resulted in a slower recovery from colitis, as shown by the slower weight gain in the recovery phase of the experiment." (PMID 37598207, 2023). "In conclusion, OTULINIEC-KO mice recover slower from DSS-induced colitis, suggesting that OTULIN is needed to reestablish the intestinal barrier stability upon acute inflammation." (PMID 37598207, 2023).
colon carcinoma (1 paper, 2016). "Analysis of THP1 human monocytic cells or HCT-116 human colon carcinoma cells, which both express NOD2 endogenously, confirmed that CYLD was not involved in controlling Met1-Ub accumulation on HOIP whereas OTULIN was indispensable." (PMID 26997266, 2016).
Cri-du-chat syndrome (1 paper, 2023). Monosomy 5p, also known as Cri du chat syndrome, is a rare autosomal deletion syndrome characterized by a mewing cry (cri du chat) in infancy, multiple congenital anomalies, intellectual disability, microcephaly, and facial dysmorphism. "Our observations suggest that it is worth considering the possibility that reduced levels of OTULIN might contribute to the scoliosis reported in 30 of the surveyed 73 cri du chat syndrome patients, who are haploinsufficient for the OTULIN-harboring region on chromosome 5p." (PMID 37589075, 2023).
Failure to thrive (1 paper, 2019). Failure to thrive (FTT) refers to a child whose physical growth is substantially below the norm. "Clinically, HOIL‐1 and OTULIN deficiency manifests similarly with neonatal‐onset systemic inflammation, recurrent fevers and failure to thrive." (PMID 30804083, 2019).
Hepatic fibrosis (1 paper, 2023). The presence of excessive fibrous connective tissue in the liver. "used hepatocyte-specific knockout of OTULIN (OtulinΔhep) mice to establish that the lack of OTULIN led to mTORC1-associated steatohepatitis, hepatic fibrosis, and cancer." (PMID 38164133, 2023).
hepatocellular carcinoma (1 paper, 2022). A malignant tumor that arises from hepatocytes. "This assumption was confirmed in mice with liver‐specific OTULIN deficiency which suffered from steatohepatitis, fibrosis, and hepatocellular carcinoma." (PMID 35170849, 2022). "This is further supported by the fact that mice with liver‐specific deletion of OTULIN show a similar disease phenotype with liver inflammation and apoptosis ultimately leading to formation of hepatocellular carcinoma." (PMID 35170849, 2022).
lipodystrophy (1 paper, 2024). A congenital or acquired disorder characterized by abnormal loss or redistribution of the adipose tissue in the body. "OTULIN deficiency is a complex disease characterized by a wide range of clinical manifestations, including skin rash, joint welling, lipodystrophy to pulmonary abscess, and sepsis shock." (PMID 38774872, 2024).
neuropathic pain (1 paper, 2024). Chronic pain caused by damage to nerve fibers. "Collectively, this study revealed the upregulation of OTULIN in an IONL‐induced neuropathic pain model and demonstrated a close association between its expression changes and the occurrence of pain behaviors." (PMID 39169794, 2024).
papilloma (1 paper, 2021). A benign epithelial neoplasm that projects above the surrounding epithelial surface and consists of villous or arborescent outgrowths of fibrovascular stroma. "Keratinocyte-intrinsic OTULIN knockout causes highly localised inflammatory lesions in the back skin, which morphologically and histologically resemble papillomas, while in mice with LUBAC deficiency the entire skin is affected and there are no signs of papilloma-like structure appearance." (PMID 34625557, 2021).
periodontitis (1 paper, 2021). An acute or chronic inflammatory process that affects the tissues that surround and support the teeth. "Our findings suggest that CYLD, A20 and OTULIN might play a role in the progression of periodontitis." (PMID 34092220, 2021). "Given the role of these DUBs in limiting inflammation, our findings suggest that CYLD, A20 and OTULIN might be involved in the pathogenesis of periodontitis and might act as potential therapeutic targets to treat periodontitis." (PMID 34092220, 2021).
Salmonella Infections (1 paper, 2023). Infections with bacteria of the genus SALMONELLA. "To assess if OTULIN-deficiency influenced cell death during Salmonella infection, we stained proximal and distal colon sections for cleaved caspase-3 or TUNEL." (PMID 37598207, 2023). "Finally, we show that OTULIN deficiency in IECs increases susceptibility to Salmonella infection, further confirming the importance of OTULIN for intestinal barrier integrity." (PMID 37598207, 2023). "Together, these findings demonstrate that OTULIN signaling within intestinal epithelial cells is critical for restricting cell death and pathogen burden in response to inflammation-inducing virulent Salmonella infection." (PMID 37598207, 2023).
sarcoma (1 paper, 2024). A usually aggressive malignant neoplasm of the soft tissue or bone. "High OTULIN expression was associated with reduced survival in sarcoma patients." (PMID 39721999, 2024).
tauopathy (1 paper, 2025). Neurodegenerative disorders involving deposition of abnormal tau protein isoforms (tau proteins) in neurons and glial cells in the brain. "To elucidate the potential roles of OTULIN in tauopathy-manifested neurodegeneration, we employed an Affinity Purification (AP)-based proteomic approach to profile the OTULIN interactome in the most commonly used mouse model of tauopathy (i.e., PS19)." (PMID 39974971, 2025). "Given the pivotal role of APL pathway in tau clearance, the potential role of OTULIN in tau degradation warrants further investigation during the development of tauopathy." (PMID 39974971, 2025). "To investigate the potential roles of OTULIN in tauopathies, we analyzed the OTULIN interactome in hippocampal tissues from PS19 transgenic (Tg) mice and their non-transgenic (nTg) littermate controls using affinity purification-mass spectrometry (AP-MS)." (PMID 39974971, 2025). "Potential implication of the enhanced interaction between OTULIN- SERCA2 in the progression of tauopathy will be further discussed later (see the discussion section)." (PMID 39974971, 2025). "To investigate the role of OTULIN and its interacting protein partners in this tauopathy model, we conducted AP-based pull-down experiments on immunoprecipitated fractions from the hippocampal tissues (a brain region most critical for memory) of PS19 Tg mice and their nTg littermate control mice." (PMID 39974971, 2025). "Deubiquitination, particularly by OTULIN, a unique deubiquitinase targeting methionine-1 (M1) linkages from linear ubiquitin chain assembly complex (LUBAC)), is reportedly associated with the accumulation of neurotoxic proteins in several neurodegenerative diseases, likely including tauopathies." (PMID 39974971, 2025). "Given the critical role of autophagic dysfunction in the development of tauopathy, we further explored the potential functional importance of SERCA in the context of the OTULIN-SERCA axis in the PS19 model." (PMID 39974971, 2025). "Indeed, we confirmed markedly enhanced OTULIN- SERCA2 interaction in late symptomatic Tg samples (10 months of age), while the direct input total SRECA2 protein abundancy was found to be reduced significantly in the Tg hippocampal samples at this late stage of tauopathy." (PMID 39974971, 2025).
trigeminal neuralgia (1 paper, 2024). Trigeminal neuralgia is a nerve disorder that causes a stabbing or electric-shock-like pain in parts of the face. "Our study reveals that OTULIN significantly mitigates neuropathic pain and neuroinflammation in trigeminal neuralgia by activating autophagy and inhibiting the NLR family pyrin domain containing 3 inflammasome, highlighting its potential as a therapeutic target." (PMID 39169794, 2024).
triple-negative breast carcinoma (1 paper, 2020). An invasive breast carcinoma which is negative for expression of estrogen receptor (ER), progesterone receptor (PR), and human epidermal growth factor receptor 2 (HER2). "Inhibiting OTULIN or Wnt/β-catenin sensitizes triple-negative breast cancer xenograft tumors to chemotherapeutics and reduces metastasis." (PMID 32770022, 2020).
vasculitis (1 paper, 2024). "Biallelic hypomorphic variants of OTULIN underlie an autoinflammatory disorder with multiple phenotypes including vasculitis, and high levels of NF-κB, TNF, IL-1β, and IL-17 production have also been observed." (PMID 39403923, 2024).
cancer (9 papers, 2016 to 2024). A tumor composed of atypical neoplastic, often pleomorphic cells that invade other tissues. "Here, we demonstrate that OTULIN loss of function leads to chemoresistance in experimental cancer models." (PMID 35939695, 2022). "Specific OTULIN deficiency can cause chronic liver inflammation and cancer in mice." (PMID 39169794, 2024). "To examine whether the NASH-like pathology in young Otulin∆hep mice might lead to cancer, we analysed the OTULIN-deficient livers for signs of neoplasia and HCC." (PMID 32231246, 2020). "Hence, a fuller understanding of the detailed molecular mechanisms underlying the disruption of the OTULIN–LUBAC interaction will be instrumental for developing future therapeutic strategies against cancer chemoresistance and necroptotic processes pertinent to numerous human diseases." (PMID 35939695, 2022). "However, it remains unknown if OTULIN deficiency also promotes development of cancer or other pathologies." (PMID 32231246, 2020). "This suggests that OTULIN normally acts to suppress HCC, and its loss can lead to cancer progression." (PMID 38419066, 2024). "To validate the importance of these interactions in cancer models, we first determined the specific domains of OTULIN and HOIP interaction under normal unstressed conditions by using a domain truncation strategy." (PMID 35939695, 2022). "Increased Wnt/β-catenin activation in TNBC cells upon chemotherapy, which is dependent on OTULIN, facilitates cancer cell adaptation to a drug-resistant state and enhances metastasis." (PMID 32770022, 2020). "Owing to the heterogeneity of clinical cancer tissues, OTULIN and LUBAC components may be dysregulated at additional multiple levels, involving transcriptional, posttranscriptional, and posttranslational mechanisms." (PMID 35939695, 2022). "OTULIN can protect the liver against cell death and cancer, OTULIN deficiency in non-hematopoietic cells causing liver pathology." (PMID 33498168, 2021). "We also found that c-Abl, the upstream kinase modulating OTULIN-mediated genotoxic Wnt activation, may also enhance drug resistance in cancer cells." (PMID 32770022, 2020). "More important, OTULIN dimerization results in a disruption of the OTULIN-HOIP interaction, leading to genotoxic NF-κB activation and increased cancer cell survival (i.e., the main feature of chemoresistance)." (PMID 35939695, 2022).
infection (9 papers, 2016 to 2025). The state of being infected such as from the introduction of a foreign agent such as serum, vaccine, antigenic substance or organism. "Our results showed that STING interacted with HOIP and Sec24b at the early stage of HSV‐1 infection and then bound to OTULIN at the late stage of the infection." (PMID 40536345, 2025). "Nonetheless, the clear roles of OTULIN in development open a new perspective upon Met1 signalling beyond inflammation and infection." (PMID 26503766, 2016). "Cytokines such as IL‐1β or stimulation of pattern‐recognition receptors mimicking pathogen infection of cells seem to be more reliant on Met1 linkages, and OTULIN, for signal transduction." (PMID 26503766, 2016). "OTULIN is critical for restraining life-threatening spontaneous inflammation, maintaining immune homeostasis and activating NF-kappaB to promote the secretion of pro-inflammatory cytokines and restricts bacterial proliferation in infection." (PMID 33255903, 2020). "This suggests that the regulation of RIPK2 ubiquitination by CYLD (and LUBAC and OTULIN) could influence the response to infection by intracellular bacteria." (PMID 26997266, 2016). "The few proteins for which a fold-change >2 or <−2 was observed 48 h after infection are involved in apoptosis (SCARF1, PLSCR3), ubiquitination (UBE2E3, OTULIN), or the response to type I IFN (OAS2)." (PMID 35337059, 2022). "Autosomal recessive OTULIN mutations cause ORAS, manifesting early in life with autoinflammation without clear evidence of infections, due to the defective downregulation of NF-κB-dependent inflammatory signaling." (PMID 38774872, 2024). "Other biologically relevant Wnt5a-dependent processes, for example, cell-specific responses to infection or SCRIB-dependent processes – including ones directing apical-basal polarity – may be impacted by the OTULIN-SCRIB interaction and Met1-Ub homeostasis." (PMID 37589075, 2023).
tumor (6 papers, 2016 to 2024). "OTULIN levels were significantly increased in tumor samples compared with that in normal breast tissues." (PMID 32770022, 2020). "In summary, we demonstrate that OTULIN prevents cell death, inflammation, and metabolic derangements in the liver and can act as a tumour suppressor in mice." (PMID 32231246, 2020). "In addition, a comparison of the mRNA expression data of paraneoplastic and tumor tissues revealed that the expression of OTULIN in tumors was significantly greater than that in paraneoplastic tissues." (PMID 39721999, 2024). "OTULIN deletion showed little effect in xenograft tumor growth, but it significantly sensitized MDA-MB-231 xenografts to Dox treatment and remarkably suppressed tumor growth." (PMID 32770022, 2020). "Additionally, the results of expression analysis on the data of Chinese Human Proteome Project (CNHPP) (110 paired tumor and nontumor tissues of clinical early‐stage HCC) showed consistently upregulation of protein level of OTUs (including OTUD7B, OTUD6B, ALG13, OTUB1, OTULIN) in HCC tissues." (PMID 32328410, 2020).
inflammation (2 papers, 2018 to 2023). Aberrant reaction of the microcirculation characterized by movement of fluid and leukocytes from the blood into extravascular tissues. "Together, these data show that OTULIN also critically controls TNF-induced cell death in a transgenic model of chronic TNF-driven intestinal inflammation." (PMID 37598207, 2023).
gynecologic tumor (1 paper, 2022). "Some of the differential NRGs are unique to a particular gynecologic tumor, such as BCL2L11 and OTULIN in CESC, MAP3K7 in OV, TLR2 in UCS." (PMID 36357839, 2022).
OTULIN also shares sentences with these, for which no sentence is quoted: Arthritis (4 papers); dermatitis (2); heart failure (2); antibody deficiency and (1); Bartsocas-Papas syndrome (1); Behcet disease (1); Blau syndrome (1); Intellectual disability (1); microcephaly (1); myopathy (1); neurodegenerative disease (1); psoriasis (1); pterygium (1); pyoderma gangrenosum (1); scoliosis (1); Sepsis (1); verrucous carcinoma (1).